CD4 (CD4 molecule)
Diseases named in the same sentence as CD4 in open-access papers (continued):
Sharing a sentence is not in itself a finding about the gene and the disease.
tumor (continued). "The CD25+CD4+FoxP3+ Treg cells are potent suppressors of antigen-specific or non-specific tumor immunity, with FoxP3 is a master gene that controls the differentiation of CD25+CD4+ T-cell and its functions." (PMID 29535722, 2018). "This promotes regulatory T cell survival and function, but inhibits the generation of effector CD4+ and CD8+ T helper cells, which may promote tumor cell growth and expansion." (PMID 29545920, 2018). "Tumor antigens are presented by the major histocompatibility complex (MHC) class I molecules on antigen-presenting cells (APCs) and recognized by CD8+ T cells, which differentiate into cytotoxic T lymphocytes under co-stimulation of CD4+ T cells." (PMID 30574154, 2018). "Also of note, tumors infiltrated by activated CD4 and CD8 T cells also contained increased infiltration by γδ T cells, which can also promote the anti-tumor immune response." (PMID 29487705, 2018). "Additionally, representative material was investigated for markers of immune response or suppression, including CD4, CD8 and FOXP3, to attempt to visualize infiltration of immune cells into the tumor environment." (PMID 29492202, 2018). "Treatment with SVX vaccine was also found to reshape the tumor microenvironment by increasing the tumor infiltration of both CD4+ and CD8+ T cells but not Treg cells therefore tipping the balance toward a highly efficient immune response." (PMID 30483475, 2018). "The tumor Ag reaches the TdLN and activates naive CD4+ T cells but the response is not efficient as the activated tumor Ag-specific CD4+ T cells are anergized or converted into pTregs." (PMID 29844317, 2018). "However, frequency of regulatory T cells (Treg, Foxp3+CD4+ T) was reduced in the tumor of Eomesfl/flCd4Cre mice, suggesting that Eomes might play a role in development or maintenance of intra-tumoral Treg cells instead of regulating effector functions of CD4+ T cells." (PMID 30619337, 2018). "The distribution of TILs changed following pIL-12 GET treatment resulting in an expansion of CD3+ T cells infiltrating in the tumor environment, which involved CD4+ and CD8+ T cells compared with no TX, EP1, EP2 and pIL-12 injection only groups." (PMID 30544810, 2018). "In advanced stages of cancer, when the disease is usually detected, CD4 and CD8 T cell responses are often ineffective and at best only slow down tumor progression due to low tumor immunogenicity, influence of the TME, or an interruption of the cancer immune cycle." (PMID 29032503, 2018). "To determine whether any of the N‐glycans present in serum reflect tumor immune status, we performed correlation analysis for the overall proportion of TILs (CD45+) and T helper cells (CD4+) within corresponding tumors." (PMID 29698574, 2018). "In particular, we demonstrate that the suppressive function of human naturally occurring CD4+ CD25+ Treg cells and tumor-derived antigen-specific CD4+ Treg cells can be reversed by TLR8 signaling pathway in DCs independent mechanism, but requires the activation of TLR8-MyD88-IRAK4 signaling pathway." (PMID 30619286, 2018). "Indeed, the presence of CD4+ and CD8+ T cells, functionally active against pre-neoplastic cells and able to recognize a pattern of specific antigens for each patient tumor, was reported in the BM of MGUS patients." (PMID 30319648, 2018). "Various studies have suggested that host CD4 and CD8 cells can also control tumor growth." (PMID 29707158, 2018). "Cancer cell- and M2 macrophages derived SDF-1 attracts Treg cells into the tumor lesion where they robustly induce FOXP3 and other Treg signature molecules in human naïve CD4+ T cells which display enhanced FOXP3 stability and low expression of pro-inflammatory cytokines." (PMID 30622535, 2018). "Because CTLA-4 is constitutively expressed on CD4+CD25+ Treg, CTLA-4 blockade might be expected to suppress Treg function and allow expansion of a tumor-specific immune response." (PMID 29973204, 2018).
tumor (continued). "MDSCs share some common features such as their myeloid origin, immature state, and most importantly, the ability to convert immune responses from a Th1 phenotype toward a Th2 phenotype, which result in potent inhibition of CD4+ and CD8+ T cells and significant immunosuppression in tumor settings." (PMID 30619286, 2018). "Due to the increased relevance of immune system components in the tumour microenvironment, we first studied the presence and phenotype of infiltrated CD14+ monocytes/macrophages, and CD4+ or CD8+ T-lymphocytes, noting that the tumour zones were significantly enriched in CD14+ cells." (PMID 30285662, 2018). "Boundary conditions We assume that naive CD4+ T cells and CD8+ T cells which migrated from the lymph nodes into the tumor microenvironment have constant densities T^8 at the tumor boundary, and that they are activated by dentritic cells and IL-12 upon entering the tumor." (PMID 29420595, 2018). "Also, at 90 days post tumor rechallenge, we found that long-term effector memory (CD4+ CD44hi CD62Llo and CD8+ CD44hi CD62Llo) was established in mice treated with radiation + anti-PD1 + anti-GITR and then rechallenged with 344SQ_R tumor cells." (PMID 30294332, 2018). "In addition, an increase in tumor infiltration of CD3+, CD8+, and CD4+ T-cells expressing granzyme was reported." (PMID 30176921, 2018). "We have found that high CXCR3 expression on circulating effector memory CD4+ T cells is associated with an enhancement of stage III-IV patient survival, irrespective of tumor lesion location and patient stages." (PMID 30420855, 2018). "The co-culture of CD4+ T cells and AML cells suggest that tumor cells themselves may act as direct APC." (PMID 30319662, 2018). "However, human CD4+ T cells can suppress tumors expressing adequate levels of MHC class II and self-antigens on their surface, through secretion of IFN-γ or direct tumor killing." (PMID 30483263, 2018). "Which of these mechanisms is more important for tumor rejection remains unclear, however the predominant dependence of murine anti-tumor activity and human IL-2 production (SEB assay) on CD4+ cells is intriguing." (PMID 30563566, 2018). "Here, we performed comprehensive immunohistochemical analysis of the local tumor infiltration level of CD4 +, CD8 +, and Foxp3 + T lymphocytes and of PD-L1 expression on tumor cells in resected specimens of eCCA, and we further analyzed their association with EMT-related protein expression." (PMID 29732001, 2018). "GSI stimulation led to the reduction in IL-22 secretion by CD4+ T cells purified from both nontumor site (135.2 ± 24.02 compared with 117.8 ± 16.40 pg/ml, P=0.041) and tumor site (264.3 ± 79.76 compared with 168.1 ± 68.41 pg/ml, P=0.003)." (PMID 30473538, 2018). "In fact, in our patient, CD4 and CD8 infiltration within the tumor was similar to that observed in post-transplant CRCs and lower than that observed in UC-related CRCs, suggesting a deep effect on cancer microenvironment of post-transplant immunosuppression regimen." (PMID 29915171, 2018). "Whereas, BDCA-1+ mDCs direct the polarization of CD4+ T helper cells, BDCA-3+ DCs are potent at cross-presenting antigens to CD8+ T cells and, therefore, have an important role in inducing T cell responses against tumor cells." (PMID 30687337, 2018). "Interestingly, activated CD4 and CD8 T cells were the most commonly infiltrating cell types, followed by mDCs, all of which are desired for an optimal anti-tumor response." (PMID 29487705, 2018). "A previous study showed that protection against tumor outgrowth by vaccination with MCMV-TRP2 was not dependent on CD8 or CD4 T cells but rather on antibodies." (PMID 30034625, 2018). "The total tumor CD3+ T cell infiltrate was unchanged (not shown); however, there was a significant decrease in the number of CD3+CD8+ T cells but not CD3+CD4+ T cells per tumor." (PMID 29725089, 2018).
tumor (continued). "Examination of tumor-associated T cells showed that IL-2/CD40 reduced young, but not elderly, CD4+ T cell and Treg proportions, leaving elevated Treg proportions in elderly IL-2/CD40-treated tumors, implying increased suppressive activity in elderly tumors." (PMID 30560130, 2018). "However, 24 hours post tumour inoculation, CD134 upregulation was observed on a proportion of NK cells and multiple T-cell subsets (NK: 26% positive, CD8+ T: 24%, effector CD4+ T: 35% and Treg: 88%)." (PMID 29396470, 2018). "When MHC class II epitopes were solely expressed by the tumor, no CD4 T cell responses were detected." (PMID 29032503, 2018). "Patients with positive E-cadherin expression had higher median cell counts of CD4+/PD-1− tumor-infiltrating lymphocytes than patients with negative E-cadherin expression (30/HPF versus 10/HPF, p < 0.05)." (PMID 30069490, 2018). "We did not observe significant changes to frequency or number of total CD4+ T cells, Treg, or myeloid-derived suppressor cell (MDSC) populations in the tumor with M7824 treatment." (PMID 29721396, 2018). "Similarly, the percentages of T and B lymphocytes differed in tumor tissue and BAL, whereas CD4+ and CD8+ subpopulations looked similar in both." (PMID 29520483, 2018). "Soluble tumor antigens acquired by DCs are trapped in endolysosomal compartments and digested into peptides, which are subsequently loaded almost entirely onto MHC class II molecules for presentation to CD4+ helper T cells." (PMID 30013560, 2018). "However, the role of immunosuppression is more difficult to predict because metastases of CT26 were decreased in CD4+ T cell-depleted BALB/c mice, suggesting that CD4+ T cells are involved in negative regulation of anti-tumor responses." (PMID 29915171, 2018). "In addition, the percentages of PD1+ CD4 T and CD8 T cells, a population reported to contain tumor-reactive lymphocytes, were greatly increased after the T-VEC plus anti-PD1 based therapy in all complete responders but not in partial responders." (PMID 29764498, 2018). "Although, the necessity of CD4+ T cell help for the cytotoxic programming of CD8+ T cells is widely appreciated, they have also been described to suppress tumor growth through the secretion of IFN-γ or direct killing of tumor cells." (PMID 30505306, 2018). "Tumor protection was observed to be CD8, as well as CD4 dependent." (PMID 30030558, 2018). "While IFN-γ production may directly inhibit tumor growth in synergy with TNF-α, it remains to be investigated whether CD103+CD4+ TILs are equally equipped to kill cancer cells as their CD103+CD8+ counterparts." (PMID 30505306, 2018). "Such distinct changes of BTLA and HVEM expressions in tumor patients were attributed to the absence of their positive correlation between CD4+ and CD8+ T cells, which can be observed in healthy donors." (PMID 30116751, 2018). "Further, activated CD4 and CD8 T cells were low in tumors infiltrated by activated B cells or immature B cells, in agreement with a study demonstrating increased CD8 tumor infiltration and decreased tumor growth after B cell depletion." (PMID 29487705, 2018). "Expression of antigens restricted to MHC class I epitopes induced strong CD8 T cell responses that were not capable of eliminating tumor cells without tumor-specific CD4 T cells." (PMID 29032503, 2018). "We observed that inhibition of EphB4-ephrin-B2 signaling in vivo significantly reduced tumor growth and decreased the infiltration of Tregs, TAMs, and increased infiltration and activation of Teffector cells, without affecting CD4 T cell numbers." (PMID 30400822, 2018). "Furthermore, immunosuppressive cells including Foxp3+ CD4+ regulatory T cells (Tregs) and myeloid‐derived suppressor cells (MDSC) in tumor microenvironments play significant roles in suppressing anticancer immunity." (PMID 30046565, 2018).
tumor (continued). "Enabling tumor progression, activated CD4+Foxp3+ regulatory T cells (Tregs) are known to migrate to the tumor site and inhibit of CD8 effector T cells (Teffs), which are mainly responsible for anti-tumor immune responses." (PMID 29673141, 2018). "Besides, there was an augment in the percentage (p<0.05) of activated CD4 and CD8 T infiltrating tumor cells in the Hybrid+P." (PMID 30300366, 2018). "Previous studies reported that CIK/DC-CIK therapy could significantly increase the proportion of CD3+ T cells, CD3+ CD4+ T cells, and the ratio of CD4+/CD8+ T cells and improve the tumor responses for NSCLC." (PMID 30648123, 2018). "Interestingly, both populations of tumor-infiltrating T cells in the MIF KD tumors were more activated, as exhibited by the ability of both CD8+ and CD4+ T cells to express IFNgamma after ex vivo re-stimulation." (PMID 29864117, 2018). "There is discordance whether thymus-derived Tregs mediate the conversion of conventional CD4 T cells to immunosuppressive Tregs by TGF-β and IL-10 or if peripherally-derived Tregs are accumulating in the tumor tissue." (PMID 29032503, 2018). "Here, we demonstrate that TGF‐β CAR‐T cells can also protect neighboring immune cells from the suppressive effects of TGF‐β by enabling tumor‐targeted CD8+ T cells to retain cytolytic activity in the presence of TGF‐β, and by discouraging CD4+ T cells from TGF‐β–induced Treg differentiation." (PMID 30065964, 2018). "The differential distributions of CD4+CD25+Foxp3+ Tregs were observed regardless of tumor region, LN metastasis and clinical staging." (PMID 30012191, 2018). "In the tumor, we found the best producers of IFN-γ to be CD103+CD4+ TILs." (PMID 30505306, 2018). "Therefore, we measured the percentages of CD4+, CD8+ and T regulatory cells (Tregs) in both peripheral blood and spleens of normal and tumor-bearing mice treated with the drug." (PMID 30079021, 2018). "Moreover, this was accompanied with important changes in the TME with a shift toward tumor-suppressing Th1-mediated immune responses, including TAM polarization to an M1-like phenotype and increased CD4+ and CD8+ T-cell tumor infiltration." (PMID 29371595, 2018). "The tumor cells that were injected subcutaneously in mice lacking NF-κB in T CD4+ cells (CD4 conditional deletion) were not rejected, as in the control mice." (PMID 29315242, 2018). "The antitumor mechanism of DC-based vaccine is that DCs could induce both CD4+ T helper cells and CD8+ CTLs resulting in activating apoptosis signal pathways in tumor cells." (PMID 30116759, 2018). "CD4+ and CD8+ T cells are the main components of tumor-specific, cellular adaptive immunity." (PMID 29499656, 2018). "In mice treated with DNA immunization and α-GalCer, antibodies against CD8, NK1.1 and IFN-γ induced tumor growth but carrageenan and anti-CD4 did not have a marked effect." (PMID 30469401, 2018). "Likewise, only MLKL-mRNA treatment resulted in significant numbers of interferon-γ (IFN-γ) producing OVA-peptide-specific CD4+ and CD8+ T cells in the tumor draining lymph node." (PMID 30143632, 2018). "The majority of CD4+ and CD8+ T cells in tumor exhibited a CD45RA−CD45RO+ effector/memory phenotype, as could be expected from T cells present in non-lymphoid organs." (PMID 30774636, 2018). "This ability of TGFβ to skew the differentiation of CD4+ T cells away from a TH1 phenotype toward a Treg lineage has significant clinical implications, as the functional orientation of tumor-infiltrating immune cells has a major impact on the outcome of patients with cancer." (PMID 29467463, 2018). "We also characterize in details these anergic CD4+ T cells with regard to lymphokine secretion and phenotype stability in the presence or absence of tumor." (PMID 29844317, 2018). "Additionally, tumor-derived EVs induce apoptosis in CD8+ T cells and enhance CD4+T regulatory cell suppressor activity." (PMID 30583481, 2018).
tumor (continued). "Tumor antigens and DC, obtained by surgical resection and leukapheresis, respectively, DCs are mixed and injected back to the patient, allowing DCs to present their surface tumor antigens to the CD4 and CD8 T-cells of the immune system, leading to the activation of T-cells against the tumor." (PMID 30271342, 2018). "Interestingly, both class I- and class II-specific blockade consistently reduced functional activity of TIL, suggesting that both CD4+ and CD8+ TILs contribute to functional activity of the expanded TILs against autologous tumour." (PMID 30039427, 2018). "The role of TILs, T effector (CD8+, CD4+) and T regulatory (FOXP3+, CTLA-4+, PD-1+) cells and CD56+ NK cells in ALNs is even less well studied and their contribution to the induction of immune-mediated tumour cell death in ALN metastases poorly documented." (PMID 29390966, 2018). "In addition, the activation and cytokine production by both CD4+Foxp3- and CD8+ tumor infiltrating T cells were markedly suppressed." (PMID 29672594, 2018). "Targeting of CD39 on Treg may also be beneficial due to the low CD39 expression on CD4+CD25− and CD4+CD25int tumor-infiltrating effector T cell subsets as previously shown." (PMID 30651930, 2018). "Thus, TGF-β produced by tBreg cells not only promotes generation of FoxP3+ Treg cells but also fully activates the regulatory function of MDSCs (i.e., increased ROS and NO production), suppresses CD4+ and CD8+ T cells, and promotes tumor growth and metastasis." (PMID 29762501, 2018). "The Tim-3+ Tregs participate in shaping tumor-immune microenvironment (TIME) through supporting development of exhausted CD8+ T cells and limiting the expansion of pro-inflammatory cytokine-secreting CD4+ and CD8+ T cells." (PMID 30309387, 2018). "Although the mechanistic basis for this observation was not addressed, it was shown that the presence of CD4+ T cells was required for the appearance of iNOS-expressing macrophages within the tumor bed following vaccination." (PMID 30083157, 2018). "Consistent with its superior antitumor efficacy, a-CTLA4-TGFβRII was more effective in reducing Tregs, elevating tumor-reactive IFN-γ-expressing CD8+ cells and increasing the CD4+ and CD8+ central memory T cells compared with the combination of a-CTLA-4 and a-PD-1 mAbs." (PMID 29467463, 2018). "In the 50% of untreated, 66.7% of BALB TB EV-treated, and 40% of BALB CD4 EV-treated B16F10 groups, or 50% of untreated and 60% of BALB CD4 EV-treated 4T1 groups, it was impossible to completely remove the tumours and these tumours invaded into the muscle or fatty layer." (PMID 29382847, 2018). "In the lungs of tumor-bearing mice, it was observed a significant increase in the numbers of CD4+Foxp3+IL-10+ and a significant decrease in ROR-γ+IL-17A+CD4+ T cells T cells in metformin-treated and protected animals, phenotypically similar to Treg and Th17 cells, respectively." (PMID 29899823, 2018). "In this co‐culture, only the CD8+ T cells have tumor‐recognition capability, since the CD4+ T cells do not express a tumor‐antigen–specific receptor." (PMID 30065964, 2018). "We detected a large number of CD14+ monocytes/macrophages with an alternative phenotype (CD64+CD163+) and CD4+ lymphocytes that infiltrated the tumour, but not the peritumour area." (PMID 30285662, 2018). "The CD4+CD25+CD127+ subpopulation was active, causing death of 20% of the tumor cells, while the CD4+CD25+CD127− subpopulation did not demonstrate any cytotoxic properties." (PMID 29850628, 2018). "But more translational studies are needed to evaluate whether RT can enhance the priming of tumor-reactive T cells in large cohorts of patients and whether they induce CD8 and CD4 immunological memory." (PMID 29383033, 2018). "Most of the responses were mediated by CD4+ T-cells, however none of the neoantigen-specific T-cells recognized cultured tumor cells in four out of six patients." (PMID 29678194, 2018).